DOLPP1 (dolichyldiphosphatase 1)
Description:
Required for efficient N-glycosylation. Necessary for maintaining optimal levels of dolichol-linked oligosaccharides. Hydrolyzes dolichyl pyrophosphate at a very high rate and dolichyl monophosphate at a much lower rate. Does not act on phosphatidate (By similarity).
Synonyms: LSFR2
Tractability: Antibody: UniProt predicts a signal peptide or a membrane-spanning region. PROTAC: its protein half-life has been measured.
Gene: Protein-coding gene on chromosome 9 (129,081,100 to 129,090,438, forward strand). Ensembl gene ENSG00000167130.
Subcellular location: Endoplasmic reticulum membrane
Subcellular location (Human Protein Atlas): Vesicles; Intermediate filaments
Pathways (Reactome):
Metabolism of proteins: Synthesis of dolichyl-phosphate
Gene Ontology:
Molecular function: dolichyldiphosphatase activity
Biological process: dolichyl monophosphate biosynthetic process; protein N-linked glycosylation
Cellular component: endoplasmic reticulum membrane
Genetic constraint (gnomAD): Loss-of-function variants: 15 observed, 33.48 expected, observed/expected ratio (o/e) 0.45, 90% interval 0.3 to 0.69. The upper end of that interval is the gene's LOEUF score, 0.69, which puts it in group 2 of 6, group 1 being the genes least tolerant of losing a copy. Missense variants: 245 observed, 304.03 expected, observed/expected ratio (o/e) 0.81, 90% interval 0.73 to 0.9. Synonymous variants: 130 observed, 129.87 expected, observed/expected ratio (o/e) 1, 90% interval 0.87 to 1.16.
Homologues: Orthologues: chimpanzee DOLPP1 (100% identical), macaque DOLPP1 (99% identical), dog DOLPP1 (96% identical), guinea pig DOLPP1 (95% identical), mouse Dolpp1 (94% identical), rat Dolpp1 (88% identical), pig DOLPP1 (87% identical), tropical clawed frog dolpp1 (76% identical), zebrafish dolpp1 (76% identical), rabbit DOLPP1 (70% identical). Paralogues in human: PPT2 (22% identical), PPT1 (19% identical).
Diseases named in the same sentence as DOLPP1 in open-access papers:
DOLPP1 is named in the same sentence as 3 diseases in open-access papers, as found by Europe PMC text mining. Sharing a sentence is not in itself a finding about the gene and the disease. The quoted sentences say what the papers report.
endometrial cancer (1 paper, 2019). Primary or metastatic malignant neoplasm involving the endometrium (mucous membrane that lines the endometrial cavity). "The selected lncRNA (LINC00958) and mRNA (DOLPP1) were both expressed at a higher level in endometrial cancer tissue than in healthy tissue samples." (PMID 31338870, 2019). "Finally, one set of ceRNAs (ie, LINC00958, miR‐761, and DOLPP1) was proven to be a potential prognostic signature in endometrial cancer." (PMID 31338870, 2019). "Our work suggests that LINC00958 may regulate DOLPP1 by “sponging” miR‐761 in endometrial cancer." (PMID 31338870, 2019). "Finally, DOLPP1, LINC00958, and miR‐761 were demonstrated to be the core ceRNAs of endometrial cancer." (PMID 31338870, 2019).
DOLPP1 also shares sentences with these, for which no sentence is quoted: cancer (1 paper); tumor (1).